INS (insulin)
Diseases named in the same sentence as INS in open-access papers (continued):
Sharing a sentence is not in itself a finding about the gene and the disease.
Hyperglycemia (continued). "Under these circumstances, the combination of diminished insulin production along with reduced insulin sensitivity leads to hyperglycemia, which is a hallmark of the IR to T2DM transition." (PMID 33212990, 2020). "Glucagon, epinephrine and cortisol as stress hormones cause hyperglycemia through stimulation of gluconeogenesis and glycogenolysis in liver, inhibition of insulin secretion and interruption of glucose absorption in muscle." (PMID 32670384, 2020). "Blocking Dilp release or its accumulation in the brain IPCs is associated with hyperglycemia, which is a characteristic of reduced insulin signaling." (PMID 32849518, 2020). "Ad-feed intake caused transient hyperinsulinemia, but ultimately impaired insulin secretion and glucose clearance leading to hyperglycemia in broiler breeder hens." (PMID 33114772, 2020). "STZ is the most commonly used agent for inducing type 1 DM because it can trigger specific necrosis of β islets of pancreatic cells that causes degranulation and reduces their ability to discharge insulin, thus, instigating hyperglycemia and nephropathy." (PMID 32792955, 2020). "At the time of the onset of DM, islet β cells continuously and excessively secrete insulin to reduce blood glucose, which eventually causes islet β cell injury and aggravates hyperglycemia." (PMID 32566690, 2020). "Chronic hyperglycemia results in a phenomenon called “glucose toxicity,” which reduces β-cell function and endogenous insulin secretion, ultimately causing impaired insulin sensitivity." (PMID 32351447, 2020). "This approach reduces hyperglycaemia, as well as the increased risk associated with large insulin and nutrition doses, which amplifies uncertainty in SI, especially as the measurement interval increases." (PMID 32349750, 2020). "In conclusion, using transesophageal atrial pacing, we demonstrated that insulin-deficient diabetic animals with mild hyperglycemia are at an increased risk of AF induction." (PMID 32903422, 2020). "Impaired postprandial metabolism and insulin sensitivity in overweight normoglycemic young adults indicates a risk of developing hyperglycemia." (PMID 31941993, 2020). "Prediabetes and T2D are characterized by persistent hyperglycemia and are caused by either an increasing degree of cellular insulin resistance or insufficient secretion of insulin in response to glycemia, by the pancreatic β-islets." (PMID 33324496, 2020). "Chronic hyperglycemia causes a deleterious effect on insulin action and secretion, largely mediated by oxidative stress damaging the pancreatic beta cells, which in turn activates a fibrogenic response." (PMID 33319051, 2020). "Lastly, IV dextrose induced severe glucose dysregulation, manifesting as hyperglycemia associated with an increase in insulin that was unable to control blood glucose, inferring a state of insulin resistance." (PMID 32977395, 2020). "It reduces the risk of high-fat diet-induced hyperglycemia via regulation of insulin secretion as well as the activities of hepatic glucose-regulating enzymes such as G6Pase and phosphoenolpyruvate carboxykinase (PEPCK)." (PMID 32685208, 2020). "NO derived from NOS2 most often causes β-cell dysfunction, impaired insulin secretion, hyperglycemia and the development of diabetes." (PMID 33374571, 2020). "A third nationwide cohort allowed us to analyze the association between insulin therapy—as a strategy to reduce hyperglycemia—and severe ROP." (PMID 33306685, 2020). "A positive energy balance, often caused by an excess of carbohydrates, leads to insulin resistance, impaired insulin secretion and hyperglycaemia." (PMID 32580710, 2020). "Dietary measures including IF, caloric restriction, and exercise, can increase body sensitivity to insulin, reduce body fat deposition, and correct abnormalities of fetal growth, which are associated with hyperglycemia." (PMID 33333828, 2020).
Hyperglycemia (continued). "In context with hyperglycemia and hyperlipidemia, the rapamycin pathway is associated with insulin signaling, and mTOR inhibitors are likely to cause insulin resistance and prevent lipid clearance from blood, which results in high lipid and glucose levels." (PMID 32578154, 2020). "Severe burn injury is often associated with systemic insulin resistance, hyperglycemia and hyperlipidemia that significantly contributes to the morbidity and mortality in burn patients." (PMID 33251224, 2020). "DM is a result of hyperglycemia that is usually caused by the defects of insulin secretion or/and insulin action." (PMID 31829413, 2020). "Hyperglucagonemia is considered to be caused by α cell resistance to the inhibitions of insulin and hyperglycemia." (PMID 33250773, 2020). "The exposure to maternal hyperglycemia also triggered the transgenerational transmission of glucose intolerance and abnormal insulin levels, with evidence of greater susceptibility to development of these conditions in F2 males." (PMID 32933073, 2020). "Impaired β-cell function and their increased apoptosis in rats kept in LL resulted in hyperglycemia and the loss of diurnal variation in insulin levels." (PMID 32751870, 2020). "The STAM model was characterized by hyperglycemia and reduced body weight with a nearly complete loss of insulin production." (PMID 32385406, 2020). "It is diagnosed with chronic hyperglycemia (heightened levels of blood glucose or blood sugar over the long term), linked to impaired insulin secretion, insulin action or both." (PMID 32258473, 2020). "In the FBS patients due to nonfunctional GLUT2 mutation, defective uptake of monosaccharides and reduced glucose-stimulated secretion of insulin from pancreatic β-cells in the fed state causes hyperglycemia and hypergalactosemia." (PMID 32877990, 2020). "A retrospective study found that adjunctive corticosteroid treatment was associated with increases in length of stay, hyperglycemia requiring insulin treatment, and drug costs in adults with MPP." (PMID 33330269, 2020). "The evidence for the superiority of this treatment is however poor and it is a clinical experience that insulin treatment during admission to hospital is associated with episodes of both hypo- and hyperglycaemia." (PMID 32539810, 2020). "It is characterized by persistent hyperglycemia and is caused either by inadequate insulin secretion from pancreatic beta cells, impaired insulin signaling, or both." (PMID 32158154, 2020). "FDM-risk variants within these selective sweeps identified GRM5 and DLG2 as candidates for beta cell dysregulation, as both are involved in glucose-stimulated insulin secretion and hyperglycaemia susceptibility in rodent and human." (PMID 33154479, 2020). "Their data showed that patients with hyperglycemia treated with insulin infusion had a lower risk of severe disease outcome than patients without insulin infusion." (PMID 33335527, 2020). "A prolonged HFD to 14 weeks, however, caused glucose intolerance and hyperglycemia due to impaired insulin secretion in response to either glucose or arginine." (PMID 32019155, 2020). "The NEFFA production flow maintains an insulin resistance state by altering insulin signaling, partly explaining the association between hyperglycemia and hypertension in diabetic participants (DH group)." (PMID 32962299, 2020). "Dysregulation of insulin or glucagon can result in loss of blood glucose control, characterized by hyperglycemia or hypoglycemia." (PMID 32296396, 2020). "Similar to the Scandinavian population, the risk of retinopathy was highest in this insulin deficient phenotype, underlying the pivotal role played by hyperglycemia secondary to insulin deficiency in the development of this microvascular complication." (PMID 32816869, 2020). "Prolonged Ad-feed intake caused transient hyperinsulinemia, but ultimately impaired insulin secretion and glucose clearance leading to hyperglycemia in broiler breeder hens." (PMID 33114772, 2020).
Hyperglycemia (continued). "The central NOS–NO system regulates insulin secretion and its peripheral action and the acute blockage of NOS in the CNS causes hyperglycemia, peripheral insulin resistance and decreased insulin secretion." (PMID 33374571, 2020). "The use of calcineurin inhibitors, such as tacrolimus and cyclosporine, is also associated with hyperglycemia due to a direct effect on insulin biosynthesis and release, and with islet cell apoptosis after toxic levels." (PMID 31876135, 2020). "Hesperetin also alleviated the abnormality caused by hyperglycemia in pancreatic β-cells, inducing a notable extension of islets, improved staining in pancreatic β-cells, and boosting the number of insulin immune-positive cells of the islets." (PMID 32977511, 2020). "Direct damage to β-cell islets has been reported when the SARS coronavirus binds to pancreatic ACE2 receptors, reducing insulin secretion and causing β-cell dysfunction and hyperglycemia." (PMID 32438687, 2020). "As mice heterozygous for NZO/DBA (N/D) had an increased propensity toward hyperglycemia and low circulating and pancreatic insulin compared to homozygous NZO/NZO (N/N) allele carriers, we concluded that the DBA genome contributed the diabetogenic gene." (PMID 33133152, 2020). "The term "diabetes mellitus" groups together a series of metabolic disorders characterized by hyperglycemia that is caused by the impairment of insulin secretion, action, or both." (PMID 32967115, 2020). "Loss of β-cell function and deficiency in insulin secretion drive hyperglycemia and metabolic dysfunction, which impose a metabolic burden on the liver, skeletal muscle, and adipose tissue." (PMID 33139628, 2020). "The QTL is characterized by hyperglycemia starting at 10 weeks of age, accompanied by hypoinsulinemia and a loss of body weight and total pancreatic insulin levels at the endpoint of the study at 16 weeks." (PMID 33133152, 2020). "Hyperglycemia and impaired glucose disposal following prolonged Ad-feed intake by broiler breeder hens can be partially attributed to impaired insulin secretion due to a loss of β-cells through apoptosis arising from lipotoxicity." (PMID 33114772, 2020). "T1DM is related to hyperglycemia caused by an absolute deficiency of insulin secretion and requires exogenous insulin administration if a patient is to survive." (PMID 32967115, 2020). "Like propionate, intravenous administration of butyrate causes hyperglycemia, but has also been found to induce a rapid and sustained increase in serum insulin in sheep." (PMID 32751524, 2020). "Although hyperglycemia is common to both type 1 and type 2 DM, insulin deficiency is a major feature in type 1 DM while hyperinsulinemia and impaired insulin signaling is more typical in type 2 DM." (PMID 32878057, 2020). "Consumption of SFD disrupted different links inthe regulation of insulin sensitivity in males and females:only in males, it caused satiated hyperinsulinemia and onlyin females – fasting hyperglycemia." (PMID 35087997, 2020). "Central leptin signaling can lower hyperglycemia in insulin-deficient rodents via multiple mechanisms, including improvements of dyslipidemia." (PMID 33071988, 2020). "An optimal insulin intervention for glycemic control is the key to reduce the risk of hyperglycemia and hypoglycemia and avoid short and long-term complications." (PMID 32899979, 2020). "The scientific basis and evidence for superiority of insulin therapy over other glucose lowering therapies is however poor and associated with episodes of both hypo- and hyperglycaemia." (PMID 32539810, 2020). "Type 1 diabetes (T1D) arises secondary to immune-driven destruction of pancreatic β-cells and manifests as insulin-deficient hyperglycemia." (PMID 32411136, 2020).
Hyperglycemia (continued). "An in vivo study comparing glucose fluctuation to constant hyperglycemia in female Goto-Kakizaki (GK) rats used twice daily intraperitoneal insulin injections to model GV and found that GV caused significantly more neuron apoptosis than hyperglycemia alone." (PMID 33371247, 2020). "Deficient first-phrase insulin secretion in early β cell dysfunction causes great postprandial hyperglycemia excursion and Chinese carbohydrate-rich diet fuels the flame." (PMID 32267843, 2020). "We confirmed that STZ injection induced type 1 diabetic features such as hyperglycemia, loss of body weight, decrease in insulin level, increase in HbA1c level, and glucose intolerance, as previously reported." (PMID 32397640, 2020). "DM is characterized by hyperglycemia due to relative or absolute deficiencies in insulin action or insulin secretion." (PMID 31936547, 2020). "In summary, T2DM is a heterogeneous and progressive disorder that represents a series of metabolic conditions associated with hyperglycemia and caused by defects in insulin secretion and/or insulin action due to a complex network of pathological conditions." (PMID 32872570, 2020). "Not only the levels of insulin and its receptor in AD patients are lower, but the hindered blood flow caused by persistent hyperglycemia in DM patients leads to cognitive impairment and dementia." (PMID 32245267, 2020). "Similar to genetic loss of ATGL, Atglistatin attenuated hyperglycemia and lipolysis and also improved insulin sensitivity after HS." (PMID 33097799, 2020). "Hyperglycaemia is caused by different mechanisms: decreased insulin production due to pancreatic hypoplasia, hepatic insulin resistance and altered glucose-sensing mechanisms." (PMID 32864159, 2020). "To study the possible mechanism underlying susceptibility of CUMS-induced depression to hyperglycemia, we then detected the hypothalamic inflammatory cytokine-IL-6 and the insulin signaling pathway." (PMID 32655424, 2020). "Type 1 DM is characterized by autoimmune-mediated loss of the insulin-producing β-cells in the pancreatic islets of Langerhans, causing insulin insufficiency and hyperglycemia." (PMID 32604774, 2020). "Type 1 diabetes (T1D) is a chronic progressive autoimmune disease characterized by T-cell-mediated pancreatic β-cell destruction, ultimately leading to absolute insulin deficiency and exogenous insulin-dependent hyperglycemia." (PMID 31582977, 2019). "As expected, leptin therapy improved the hyperglycemia and hyperketonemia caused by ID in Tlr4+/+ controls; yet, similar outcomes were observed in insulin deficient Tlr4−/− mice." (PMID 31391467, 2019). "Production of these “IAS-like” insulin antibodies causes marked glycemic fluctuations with postprandial hyperglycemia and fasting hypoglycemia." (PMID 30621663, 2019). "In females with T1D, there is an increased risk of hyperglycemia and decreased insulin sensitivity in the luteal phase compared to the follicular phase." (PMID 31835538, 2019). "Studies found that astaxanthin reduces the oxidative stress caused by hyperglycemia in pancreatic β-cells and improves glucose and serum insulin levels in diabetes." (PMID 31814873, 2019). "T2D is characterized by hyperglycemia caused by impaired insulin production by pancreatic beta cells and insulin-mediated suppression of glucose production in the liver." (PMID 31653062, 2019). "The patients present with intractable hyperglycemia, very low insulin secretion and undetectable islet cell antibodies causing neonatal diabetes." (PMID 31453022, 2019). "In the present study, resveratrol therapy was associated with increased fasting blood insulin levels in GK rats with a concomitant decrease of hyperglycemia." (PMID 31623226, 2019). "The most frequent cause was insulin administration for hyperkalemia and uncomplicated hyperglycemia." (PMID 31539342, 2019).
Hyperglycemia (continued). "These factors lead to persistent hyperglycemia and a subsequent decrease in insulin sensitivity, which in turn causes a series of metabolic disorders." (PMID 30823412, 2019). "The metabolic biomarkers were more strongly associated with deterioration in post-load glucose and insulin resistance than with future fasting hyperglycaemia." (PMID 31584131, 2019). "The effects of such excess glucose include the relatively early limitation of the ultrafiltration capacity of the peritoneal membrane, and the metabolic effects associated with hyperglycemia, e.g., decreased insulin sensitivity." (PMID 31547545, 2019). "DM diagnosis can be confirmed by hyperglycemia (fasting hypergly-cemia with blood sugar higher than 130 mg/dl and postprandial hyperglycemia with blood sugar higher than 180 mg/dl) resulted from deficiencies in secretion and action of insulin." (PMID 32351908, 2019). "DM is a chronic metabolic disorder characterised by deficiency of insulin or insulin action leading to hyperglycaemia." (PMID 31093501, 2019). "But this is because prolonged fasting (starvation) leads to decreased insulin secretion and to insulin resistance, and subsequent re-feeding then causes transient hyperglycemia and glycosuria." (PMID 31586989, 2019). "GDM is characterized by an exacerbation of this physiological insulin resistance state associated with an insufficient insulin secretion, ultimately resulting in hyperglycaemia." (PMID 31164969, 2019). "In mice, loss of Gpd2 is associated with decreased insulin secretion; loss of Neurod1 is associated with hyperglycemia; loss of Mapk8ip1 is associated with abnormal gluconeogenesis and increased insulin sensitivity." (PMID 31776723, 2019). "Mutant Atg7 mice also exhibit reduced β cell mass, reduced insulin circulation, and glucose intolerance, indicating that autophagy defects can reduce insulin levels and cause hyperglycemia." (PMID 31277291, 2019). "It was reported in STZ-induced diabetic rats, the STZ-induced insulin-deficient hyperglycemia caused activation of NF-κB." (PMID 31552773, 2019). "The implication of mitochondria in insulin release and the exposure of pancreatic β-cells to hyperglycemia make them especially susceptible to oxidative stress and mitochondrial dysfunction." (PMID 31487953, 2019). "A progressive decrease in insulin and proinsulin occurred following diabetes onset and was therefore associated with hyperglycemia and increased β cell death." (PMID 30842440, 2019). "To investigate if hyperglycemia effects the production/formation of AGEs within the testis and epididymis of insulin deficient Ins2Akita+/− mice we examined the AGE formation pathway in a comprehensive manner." (PMID 31506549, 2019). "The pro-inflammatory state associated with infections like TB is also linked to increased release of counter regulatory stress hormones like cortisol and epinephrine which cause reactionary hyperglycaemia due to their antagonistic effects to insulin." (PMID 30783538, 2019). "Insulin replacement therapy is necessary at the acute state of insulin deficient and hyperglycemia crisis." (PMID 31232947, 2019). "Double allele knockout of the mouse SLC2A2 gene resulted in severe hyperglycemia, low insulin, and high glucagon in the blood." (PMID 31540540, 2019). "Persistent hyperglycemia is causally associated with pancreatic β-cell dysfunction and loss of pancreatic insulin." (PMID 31061431, 2019). "The most frequent cause of iatrogenic hypoglycemia was insulin administration, for both uncomplicated hyperglycemia and for hyperkalemia." (PMID 31539342, 2019). "T2DM is rapidly increasing throughout the world and is characterized by hyperglycemia caused by defects in insulin secretion, insulin action, or both." (PMID 31137773, 2019). "CGM, in some cases, also provided insight into daily trends like overnight hypo- or hyperglycemia and caused them to change their insulin doses or behaviors in an attempt to remedy out-of-range glucose levels." (PMID 31127724, 2019).